CXCR4 (C-X-C motif chemokine receptor 4)
Diseases named in the same sentence as CXCR4 in open-access papers (continued):
Sharing a sentence is not in itself a finding about the gene and the disease.
cancer (continued). "These cancer cells, in turn, secrete chemokine receptors such as CXCR4 and CXCR7." (PMID 38788027, 2024). "The cytotoxicity and MRI results indicate that anti-CXCR4-NaGdF4 NDs could be used as efficient agents for T1-weighted MRI-guided biotherapy of cancer." (PMID 38982161, 2024). "CXCR4, JUNB and PD-L1 are implicated in cancer progression and metastasis." (PMID 38727318, 2024). "Thus, the CXCL12/CXCR4 axis has become a compelling target for novel cancer therapies to enhance treatment efficacy and prevent metastasis." (PMID 39070795, 2024). "The CXCL12/CXCR4 complex is a key factor in migration and survival of PCa cells, and indeed CXCR4 inhibitors induce apoptosis of the oncogenic cells and the suppression of cancer proliferation and vascularization." (PMID 36614308, 2023). "It has been previously reported that CXCR4 level is elevated in various cancer cell types." (PMID 36882818, 2023). "Moreover, CAF-derived CXCL12 can bind to cancer cell-derived CXCR4, activating the CXCR4/CXCL12 axis and promoting CSC phenotypes, including its proliferation, invasion and metastasis." (PMID 38455361, 2023). "Baicalin treatment exhibited the reduced CXCR4 mRNA expression on the different cancer cell lines." (PMID 38094052, 2023). "Taken together, these results suggest that CXCR4 function may be inhibited by LPA1 in cancer tissues as well as in cancer cell lines." (PMID 37749552, 2023). "CXCL12, also known as stromal cell-derived factor-1 (SDF-1), is an extracellular homeostatic chemokine that often binds to CXCR4, which could regulate cancer cell malignant progression." (PMID 38057830, 2023). "Given that CXCR4 is an important therapeutic target for the treatment of cancer and immune-related diseases, further identification of CXCR4 heteromers and comprehensive understanding of their physiological relevance will provide valuable insights for the advancement of future therapeutics." (PMID 37749552, 2023). "Moreover, HIF-1α directly regulates the transcription of CXCR4, a chemokine receptor involved in cancer cell migration, invasion and in the maintenance of CICs in different solid tumors." (PMID 37838700, 2023). "Overexpression of CXCR4 is present in the majority of cancers." (PMID 37375261, 2023). "The CXCL12/CXCR4 biological axis plays an important role in the malignant progression of cancer." (PMID 38057830, 2023). "Furthermore, our data raise concerns about the potential complications in using LPA1 antagonists for the treatment of cancer or inflammatory diseases that require the inhibition of both CXCR4 and LPA1." (PMID 37749552, 2023). "Moreover, the inhibition of adenylate cyclase and consequent cAMP formation, induced by the CXCL12/CXCR4 complex, favors cancer cell proliferation." (PMID 37240258, 2023). "Moreover, RKIP inhibition in CLL leads to elimination of CXCR4 expression by cancer cells, whereas RKIP was shown to play an important role in controlling mast cell-mediated allergic responses, specifically by negatively regulating mast cell activation." (PMID 37894300, 2023). "By disrupting receptor phosphorylation, CTCE‐9908 previously inhibited cellular responses associated with downstream signalling pathways of the CXCL12/CXCR4 axis and ultimately resulted in decreased levels of adhesion, proliferation and migration in several cancers." (PMID 37170733, 2023). "The results demonstrated that CAFs cause infiltration of MOs via the CXCL12/CXCR4 pathway followed by their differentiation to M2 phenotype, which implies the potential of CXCL12-mediated macrophage recruitment as a novel target for cancer therapy." (PMID 38313431, 2023). "Also, elevated CXCR4 expressionhas been associated with poor disease prognosis, whichsuggests imaging and quantification of CXCR4 levels to be clinicallyrelevant for the management of patients with CXCR4-expressing malignancies." (PMID 37328158, 2023). "The upregulation of CXCR4 also aids in the transendothelial migration of cancer cells." (PMID 37490147, 2023).
cancer (continued). "The role of CXCR4 in cancer is critical, particularly in promoting cancer cell proliferation." (PMID 37892020, 2023). "Previous preclinical studies showed that SDF1α/CXCR4 axis could mediate PCa metastasis (most often to the bones) and cancer resistance to RT." (PMID 36831366, 2023). "Moreover, CXCR4 is overexpressed in more than 70% of cancers, making it an ideal target for personalized treatments." (PMID 37047831, 2023). "MiR-125b upregulation strongly induces EMT and cancer invasion and promotes CXCR4 production." (PMID 37375460, 2023). "US clinical trials using CXCR4 targeting drugs for cancer treatment." (PMID 37114134, 2023). "Furthermore, the repressed expressions of growth factor TGFb, transcription factor STAT3 and elevated expressions of TNFa, IFNg, CXCR4 together promoted the anti-cancer efficacy." (PMID 37143538, 2023). "Similarly, silencing of CXCR4 impedes cancer progression and increases cisplatin sensitivity in ccRCC." (PMID 37679715, 2023). "In addition, nine out of ten miR candidates best describing CXCR4 overexpression within the pan-cancer cohort were reported to regulate immune-related target genes such as PD-L1 (CD274)—thereby confirming ML results based on mRNA expression." (PMID 36672341, 2023). "Previous studies have shown that intracellular delivery of siRNA to knockdown CXCR4 expression could be a therapeutic strategy in cancer cells." (PMID 38004925, 2023). "Notably, the invasion and metastasis of cancer cells in mice overexpressing both CXCR4 and CXCR7 were significantly reduced, possibly due to the distinct roles of CXCR4 and CXCR7 in metastasis." (PMID 37497001, 2023). "Pathological alterations in cancer cells, such as metastasis development and aberrant blood vessel expansion, may be facilitated by CXCR4-mediated communication." (PMID 36992255, 2023). "Hence, CXCL12 and CXCR4 can be considered as key therapeutic targets for mBC to reduce the metastasis rate of cancer." (PMID 37497001, 2023). "Current studies showed that Tregs with CXCR4 overexpression can be seen in several types of cancers which could explain why Tregs are recruited by SDF-1 at the site of tumorigenesis." (PMID 37790751, 2023). "Functional CXCL12 knockdown or the CXCR4 antagonist AMD3100 decreases the survival of cancer cells." (PMID 36980201, 2023). "CXCR4, a chemokine receptor expressed by most cancer types, including cancers of epithelial, mesenchymal and hematopoietic origin, has a critical role in cell migration and metastasis to organs that secrete its ligand, CXCL12, also known as stromal cell-derived factor-1 (SDF-1)." (PMID 37371036, 2023). "In addition, several reports have shown that the CXCL12/CXCR4 axis is involved in breast and prostate cancer cells’ metastasis to bone, where high expression of CXCR4, the receptor for the CXCL12 chemokine, is detected." (PMID 36826044, 2023). "Furthermore, the repressed expressions of TGFb, STAT3 and elevated expressions of TNFa, IFNg, CXCR4 together promoted the anti-cancer efficacy." (PMID 37143538, 2023). "Thus, their anticancer activity is due to a direct interaction with the receptor, leading to the inhibition of survival and proliferative pathways downstream of CXCR4 that maintain the cancer state." (PMID 36986589, 2023). "It was found that X4-2-6 peptide-based nanoparticles could inhibit CXCR4 function in vitro and hamper CXCR4-dependent bone metastasis of MDA-MB-231 cancer cells and prolong the survival in a mouse model of metastatic breast cancer." (PMID 36762192, 2023). "Moreover, our findings propose a therapeutic potential in combined CXCR4 and LPA1 inhibitors for cancer and inflammatory diseases associated with these receptors, simultaneously raising concerns about the use of LPA1 antagonists alone for such conditions." (PMID 37749552, 2023).
cancer (continued). "The intricate interaction between ADMSCs and cancer cells not only drives the differentiation of ADMSCs into cancer-associated fibroblasts (CAFs) but also the metastasis of cancer cells, which is attributed to the CXCL12/CXCR4 axis." (PMID 38004606, 2023). "Notably, HIF-1α has also been described to regulate self-renewal of CICs, supporting their maintenance and cancer progression and also directly regulates CXCR4 expression." (PMID 37838700, 2023). "The CXC chemokine receptor 4 (CXCR4) is a promising cancer treatment target." (PMID 36831405, 2023). "These ligands in particular are such as those involved in the context of adhesion molecules expressed on CD133+/− (CXCR4-) medullablastoma cancer stem cells (HTB-186 that expressed ICAM-1, VCAM-1, LFA-3), susceptible to natural killer (NK) cell mediated activity-killing." (PMID 38155835, 2023). "Moreover, previous studies have suggested that curcumin can interfere with the metastasis of cancer cells by inhibiting the CXCL12/CXCR4 axis." (PMID 38004606, 2023). "Like most chemokine receptors, CXCR4 contributes to inflammatory diseases and cancers." (PMID 37627560, 2023). "Finally, the TIMER2.0 web resource was used to investigate CD8+ T cell infiltration related to CXCR4 expression in the TCGA pan-cancer cohort." (PMID 36672341, 2023). "Remarkably, multivalency confers the capacity to selectively internalize in CXCR4-overexpressing (CXCR4+) cells, showing a dramatically high uptake in CXCR4+ cancer tissues that reaches around 80% of the injected dose (%ID), with negligible distribution in normal tissues." (PMID 36986589, 2023). "In combination, our pan-cancer solid tumor approach showed that overexpression of CXCR4 or FAP lead to detectable transcriptional changes (in terms of mRNA and miRNA), reflected by gene signatures best distinguishing high- and low-expressing samples in RF models." (PMID 36672341, 2023). "Some cancer therapies target CXCR4 to inhibit the growth and spread of cancer cells." (PMID 37538932, 2023). "Alternatively, metformin may preferentially target cancer cells with aberrant mTOR activation induced by the CXCL12/CXCR4-mediated pathway." (PMID 37760498, 2023). "Patients expressing high levels of CXCR4 in these cancers also had high levels of LPAR1 (right)." (PMID 37749552, 2023). "The CXCL12/CXCR4 axis plays a critical role in the pathogenesis of cancer metastasis." (PMID 37227446, 2023). "For example, in the TME, the high levels of CXCL12, which binds its seven-transmembrane receptor, CXCR4, and the low levels of adiponectin may concomitantly contribute to mediating cancer cell growth and progression." (PMID 37240258, 2023). "Preliminary in vivo experiments suggested that CXCR4 might be essential in the development of a range of cancer malignancies." (PMID 37908977, 2023). "This may be a new perspective to explore the immune mechanism and immunotherapy for cancer.Notably, studies have reported Notch signaling has been implied in mediating chemotaxis system CXCL12/CXCR4 promoted carcinoma metastasis and multiple myelom." (PMID 37932706, 2023). "Another study independently confirmed that CXCR4 antagonism with plerixafor (AMD3100) enhances T cell infiltration by releasing trapped CXCR4-expressing T cells in CXCL12-rich stroma before reaching carcinoma cells." (PMID 37966614, 2023). "Cancer cells of luminal BC communicate with immune cells through CXCL12_CXCR4." (PMID 36077333, 2022). "The assessment of CXCR4 expression in cancer tissue before surgical resection could give valuable information about the risk of potential lymph-node metastases, including lymph-node micrometastasis (LNMM)." (PMID 35877436, 2022). "However, the specific role played by CXCR4 in neutrophil function in cancer has been investigated in a limited number of studies." (PMID 35158948, 2022). "In addition, we can find that its expression positively related to multiple chemokines receptors in pan-cancer, such as CXCR4, CCR1, and CCR10." (PMID 36105106, 2022).
cancer (continued). "Generally, CXCR4’s high expression in cancers is related to a poor prognosis." (PMID 35388021, 2022). "In addition, treatment of colon cells with chemotherapy/radiochemotherapy induced a population of CD133+CXCR4+ cells, supposed to be stem-resistant cancer cells, while adding Pep R reduced this population." (PMID 35406582, 2022). "Ours is the first report of a direct interaction between PD-1 and CXCR4 in cancer cells." (PMID 35797269, 2022). "The CXCL12/CXCR4 axis is important in cancer progression and immunosuppression." (PMID 36010899, 2022). "Our discovery of the upregulation of CXCR4 expression in the hepatic metastases, and the novel imaging methodology are expected to fill the major gap in non-invasive and precise detection of early-stage liver metastases for cancer management." (PMID 35145271, 2022). "In addition, CXCR4 also enhances vasculogenesis and hypoxia-driven angiogenesis through the recruitment of CXCR4-positive pro-angiogenic cells, which also promote the spread of cancer cells." (PMID 36140541, 2022). "In addition, SERPINH1 also related to their receptors in pan-cancer, such as CXCR4, CCR1, and CCR10." (PMID 36105106, 2022). "Since CXCR4 is overexpressed on the surface of hematological cancer cells, 177Lu- and 90Y-labeled Pentixather have been evaluated as adjunct to high-dose chemotherapy in this cancer type." (PMID 35788730, 2022). "These nanoparticles are capable of selectively delivering conjugated drugs or cytotoxic protein domains to cancer cells that overexpress the CXCR4 receptor (CXCR4+) in cancer tissues, avoiding their delivery in healthy organs because of the low or negligible CXCR4 expression level in normal cells." (PMID 36612081, 2022). "In addition, the organs and tissues that possess high levels of SDF‐1, such as liver, lung, bone marrow, and lymph nodes, attract the migration of CXCR4‐expressing cancer cells." (PMID 36254250, 2022). "Hence, this study aimed to investigate CXCL12, CXCR4, and FAPα and their value as cancer survival factors in LARC after nCRT." (PMID 34976180, 2022). "Finally, using the Cistrome Data Browser, we also found that c-MYC bound and regulated the expression of CXCR4 in several different human cancer cell lines." (PMID 35853880, 2022). "Reportedly, high CXCR4 expression was integral to cancer cell migration and invasion." (PMID 35729596, 2022). "Moreover, some of these CXCR4+ cells were also positive for human-vimentin expression, implying that they were cancer cells." (PMID 35456719, 2022). "Thus, the selective elimination of these highly metastatic CXCR4+ cancer cells would potentially block metastatic dissemination." (PMID 35456719, 2022). "Conversely, increased CXCR4 activities have been observed in many cancers, including CRC." (PMID 36290780, 2022). "CXCL12/CXCR4 signaling induces the migration and stemness of cancer cells." (PMID 34927784, 2022). "We observed co-expression of PD-1 and CXCR4 in both cancer models." (PMID 35797269, 2022). "The interplay between CXCL12 and CXCR4 induces the forming of metastasis cancers." (PMID 36211359, 2022). "The overexpression of SDF1 or CXCR4 reduces muscle atrophy and increases muscle fiber diameter, implying that activation of the CXCR4 pathway may circumvent the muscle wasting seen in cancer." (PMID 36077789, 2022). "Many human cancers have high expressions of CXCR4 and integrin αvβ3, suggesting 68Ga-yG5-RGD may be useful for a broad range of applications and have good prospects for clinical translation." (PMID 36145541, 2022). "Additionally, CXCR4 expression predicts recurrence-free and cancer-related survival in nCRT-treated LARC patients." (PMID 34976180, 2022). "For cancer patients exhibiting high CXCR4 expression, the ability to target CXCR4 may be a promising approach to new therapies." (PMID 35145271, 2022). "The CXCL12 chemokine is highly expressed in the lungs and attracts CXCR4-expressing cancer cells." (PMID 35203510, 2022).
cancer (continued). "Thus, high CXCR4 expression in cancer stem cells (CSCs) will drive metastasis to tissues with high CXCL12 expression, such as the liver, lymph nodes, and bones." (PMID 35269786, 2022). "SDF-1 is an important niche factor in IL-7-expressing CAFs, indicating that the CXCL12 (SDF-1)/CXCR4 pathway may be a useful anti-cancer stem cell therapeutic (anti-CSC) target." (PMID 35735628, 2022). "It has been further demonstrated that there is a positive feedback loop between mTOR activation and the binding of CXCL12 to its receptor CXCR4—inhibiting the mTOR activity may prevent cancer metastasis because it subsequently decreases CXCL12 interaction." (PMID 36168036, 2022). "We also demonstrated that CXCR4 and, to a greater extent, ACKR3, promote the glucose metabolism through glycolysis and the pentose phosphate pathway, processes associated with the proliferation of cancer cells." (PMID 35681470, 2022). "Thus, drugs targeting CXCR4 and/or CXCR7 can influence cancer progression pathways by regulating the CXCR4/CXCR7–CXCL12 axis." (PMID 35702353, 2022). "In this setting, CXCL12 could establish a chemotactic gradient between the primary and metastatic sites, facilitating the transfer of CXCR4-positive cancer cells into tissues rich in CXCL12." (PMID 35729596, 2022). "Furthermore, AMD3100 maintained its significant CXCR4 inhibitory effect, thus impeding metastasis and the invasion of cancer cells." (PMID 35893797, 2022). "CXCR4 is expressed in a variety of cell types, including lymphocytes, hematopoietic stem cells, endothelial cells, epithelial cells, stromal fibroblasts, and cancer cells; the expression of CXCR4 is upregulated under conditions of hypoxia, stress, and injury." (PMID 35893797, 2022). "Activation of the CXCL12/CXCR4 axis is related to the potential progression of cancer." (PMID 35836256, 2022). "CXCR4 antagonist, AMD3100, could inhibit cancer cell proliferation and M2 polarization by impeding the CXCR4/stromal cell-derived factor 1α (SDF-1α) axis." (PMID 36613878, 2022). "This may also apply to dosing of “cold” CXCR4 inhibitors currently used as anti-cancer drugs, e.g., Plerixafor or Olaptesed pegol." (PMID 35312939, 2022). "In addition, the successful application of CXCR4-directed theranostics in hematologic malignancies makes CXCR4 a promising target in other types of cancers." (PMID 35565232, 2022). "Therefore, increased expression of the CXCR4/CXCL12 axis promotes cancer progression; hence patients with higher CXCR4 expression exhibit chemoresistance and reduced progression-free survival (PFS) and OS." (PMID 35269786, 2022). "CXCR4 overexpression has been reported in more than 20 human cancers, including T‐ALL." (PMID 36054080, 2022). "Cancer cell CXCR4 expression is mediated at least in part via Akt, HIF-1α, and NF-kB." (PMID 36077755, 2022). "Moreover, CXCR4 overexpression in HNSCC cancer cells compared to healthy tissue makes it an ideal entryway for targeted drug delivery." (PMID 35456719, 2022). "Interestingly, the Multivariate Cox regression analysis showed that a high pCXCR4/CXCR4 TIC ratio in primary cancer independently predicts longer RFS (HR 0.33; 95CI 0.13 - 0.81; p = 0.015)." (PMID 35397601, 2022). "AMD3100, a CXCR4 inhibitor, could suppress cancer cell proliferation and M2-TAM polarization by blocking SDF1α/CXCR4 pathway." (PMID 36014696, 2022). "CXCR4, an important regulator of the homing and mobilization of hematopoietic cell, is widely expressed on different cell types like megakaryocytes, embryonic stem cells, vascular endothelial cells, and cancer cells." (PMID 35978426, 2022). "Moreover, EPI-X4 antagonizes CXCL12-dependent signaling and migration of cancer and immune cells and serves as a CXCR4 inverse agonist as the peptide reduces basal G-protein signaling in the absence of the chemokine." (PMID 36499357, 2022). "In addition, there were some strong CXCR4 inhibitors which as adjuvant treatments for anticancer therapies against human cancer." (PMID 35978426, 2022).